INS (insulin)
Diseases named in the same sentence as INS in open-access papers (continued):
Sharing a sentence is not in itself a finding about the gene and the disease.
Insulin resistance (continued). "As our results suggested that reduced hyperinsulinemia and elevated HOMA-IR index were found in genistein-treated HFD mice, we hypothesized that the hepatic insulin signaling pathway might contribute to the improvement of insulin resistance by genistein administration." (PMID 36570152, 2022). "MasR deficiency can lead to decreased expression of glucose transporter 4, decreased insulin sensitivity, decreased utilization of glucose in adipose tissue, and decreased tolerance to high glucose, thereby leading to glucose and lipid metabolism disorders and aggravating insulin resistance." (PMID 36699034, 2022). "However, a better longtime goal should be to improve the insulin resistance of the type 2 diabetics, since the secondary health issues are more likely the result of a weakened signal-transduction of insulin, leading to inefficient functioning of anabolic pathways." (PMID 35216316, 2022). "However, the functions of EVs depend on their compositions, such as p-s-IRS and p-y-IRS; therefore, exercise or medication interventions may reverse insulin resistance by blocking the transmission of insulin signaling by altering the cargoes of EVs." (PMID 36699697, 2022). "Importantly, the insulin resistance that occurs in the natural history of the metabolic syndrome is selective, reducing some aspects of insulin signaling, while leaving others to respond further to the increases in prevailing insulin levels." (PMID 34863942, 2022). "Therefore, oxidative stress, which activates stress response pathways involving a series of serine/threonine kinases (leading cells to insulin resistance), decreases and insulin signaling may enhance." (PMID 36432465, 2022). "Moreover, the serum levels of total cholesterol, low-density lipoprotein cholesterol (LDL-cholesterol), high-density lipoprotein cholesterol (HDL-cholesterol), triglycerides, fasting glucose, insulin, c-peptide, and homeostasis model assessment for insulin resistance (HOMA-IR) were evaluated." (PMID 35639706, 2022). "Persons with T1D lack endogenous insulin secretion; varying degrees of insulin resistance could lead to increased glycemic variability (within-day glucose fluctuations), a factor reported to be associated with increased microvascular complications and cardiovascular events in T1D." (PMID 35986415, 2022). "Additionally, the common therapies used to treat T2DM (e.g., sulphonyl urea derivatives, thiazolidinediones and insulin) may, in addition, lead to weight gain and subsequent insulin resistance." (PMID 35629157, 2022). "Also, increased expression of SELENOS could contribute to insulin resistance in the liver, characterized by reduced glucose uptake, basal and insulin-stimulated glycogen synthesis, and glycogen content." (PMID 36358477, 2022). "Meanwhile, for pregnant women with T2DM, metformin could be used in cases in which diet and exercise cannot control blood glucose to the target range, or in those with significant insulin resistance with increased insulin dose but limited effect on blood glucose control." (PMID 36530712, 2022). "Importantly, metformin use in pregnancy might enhance insulin sensitivity, reduce insulin resistance and fetal hyperinsulinemia and in turn, reduce neonatal adiposity." (PMID 36733795, 2022). "In mice, liver-specific Lpl overexpression leads to a doubling of liver triglyceride content and insulin resistance, suggesting that a reduction in Lpl, such as observed with praliciguat treatment, might be involved in reducing insulin resistance or might be a marker of improved insulin sensitivity." (PMID 35308230, 2022).
Insulin resistance (continued). "While these studies show promise for biomarkers of cognitive impairment, whether the biomarkers correlate with post-mortem analysis of classic assays for CNS insulin resistance, including insulin-stimulated IR pathway activation or total IR pathway protein changes, remains to be determined." (PMID 35884888, 2022). "Indeed, it would seem to improve insulin sensitivity and reduce insulin resistance." (PMID 36615744, 2022). "In other words, SFFs could improve insulin sensitivity and insulin resistance." (PMID 35873798, 2022). "In addition to triggering insulin resistance in adipose tissues, macrophage polarization has also been found to modulate the function of β cells, the cells in the pancreas that produce and release insulin in response to elevated blood glucose levels." (PMID 39872753, 2022). "However, bee bread supplementation significantly decreased (p < 0.05) blood glucose and insulin levels as well as improved the insulin resistance as shown by the reduced (p < 0.05) HOMA-IR index and those effects were also present in the OB + OR group, except for the HOMA-IR index." (PMID 36358563, 2022). "Our results indicate that co‐treatment with metformin can counteract consequences of rapamycin‐driven hepatic insulin resistance and protect pancreatic islets from aspects of rapamycin‐driven pancreatic impairment while sustaining potentially beneficial reduction of circulating levels of insulin." (PMID 35986566, 2022). "However, the enhancement of lipolysis may result in an increase in the fatty acid, which, in turn, enters the blood circulation, further disturbing the muscular function and insulin signaling and eventually leading to the problem of insulin resistance." (PMID 35382382, 2022). "Indeed, insulin resistance has been observed in several animal models of cancer cachexia and in cancer patients, indicating that the dysregulation of insulin signaling might be connected to cancer cachexia." (PMID 35319749, 2022). "HOMA-IR, which is a surrogate of hepatic insulin resistance, was significantly lower in SG than in sham-operated animals (13.40 ± 0.57 and 39.55 ± 3.24, respectively; P = 0.0079 Holm-Bonferroni method), showing a much better hepatic insulin sensitivity following SG." (PMID 35131692, 2022). "Thus, we asked how the context-dependent glucose-stimulated insulin hyper-secretion induced by targeted β-cell specific insulin resistance may affect insulin sensitivity, adiposity, and body mass over time." (PMID 35136059, 2022). "T1D is caused by autoimmune-cell destruction and no insulin secretion, whereas T2D is caused by insulin resistance, where insulin is secreted, but the pancreas loses function, and peripheral tissues and organs such as the liver, muscles, and adipose tissue have a reduced ability to respond." (PMID 36145077, 2022). "Consequently, excess fatty acid influx into skeletal muscle and liver promotes diacylglycerol-induced insulin resistance, which impairs insulin signaling via increased insulin receptor serine phosphorylation, and worsens with disrupted mitochondrial oxidative phosphorylation." (PMID 35012577, 2022). "Reduced insulin clearance has also been reported to occur as fat deposition increases in the liver, supporting its significant role in chronic hyperinsulinemia in non-alcoholic fatty liver disease (NAFLD), a metabolic disorder that is commonly associated with insulin resistance." (PMID 36009446, 2022). "In general, maternal stress and exposure to elevated plasma corticosterone levels in different models may program insulin resistance and insulin sensitivity in the offspring which may be attributed to alterations in insulin receptor signaling pathway in peripheral tissues." (PMID 35869151, 2022). "Therefore, it may be more challenging to control blood glucose during pregnancy in patients who had been overweight or obese before becoming pregnant due to more severe insulin resistance and a subsequent increase in the use of insulin." (PMID 36960096, 2022).
Insulin resistance (continued). "The physiological importance of PTP1B in the insulin signalling pathway was previously established by the findings that the deletion of PTP1B results in insulin hypersensitivity and that overexpression of PTP1B causes insulin resistance, similar to that observed in patients with type 2 diabetes." (PMID 34208786, 2021). "In mice, obesity and the associated visceral adipose tissue inflammation result in insulin resistance, a process that appears to be mediated via increased synthesis and release of hepatic DPP4, since eliminating hepatocyte DPP4 expression suppresses inflammation and improves insulin sensitivity." (PMID 33691757, 2021). "Similarly, insulin signaling is a critical mediator of neurogenesis and hippocampal plasticity, and one of the primary mechanisms by which galantamine is thought to improve hippocampal physiology is through alleviating insulin resistance." (PMID 34530858, 2021). "However, it is clear that rodent β-cells differ from human β-cells in parameters such as response to different stressors, proliferative capacity under insulin resistance, glucose uptake, kinetics of insulin secretion, cellular composition and architectural distribution, and transcriptional profile." (PMID 33670429, 2021). "Besides insulin resistance, which leads to more insulin demand and higher blood-glucose levels, we focused on the presence of amyloidogenic aggregates in the pancreatic islets which are mainly composed of accumulated islet amyloid polypeptide (IAPP), also known as amylin." (PMID 34835247, 2021). "In addition, HOMA-IR values in prediabetic subjects have been shown to be significantly reduced following exercise compared to those in a control group, and insulin secretion adjusts in an exercise intensity-dependent manner relative to the level of insulin resistance." (PMID 34488728, 2021). "However, when pregnant (a state of insulin resistance) she again required insulin." (PMID 34032641, 2021). "In addition, sedentary behaviour and obesity-related insulin resistance, higher circulating levels of insulin and glucose, and enhancement of insulin-like growth factor 1 (IGF-1) are likely to boost cancer growth through involvement in cell differentiation, proliferation and apoptosis." (PMID 33492550, 2021). "For instance, if defective autophagy induces insulin resistance, a promising strategy for such patients may be to treat hyperglycemia with short-term intensive insulin therapy, since autophagy is already defective, and this treatment has proven effective in the control of glucose levels." (PMID 34141709, 2021). "Therefore, sulfonylureas, as well as high-dose insulin therapy, could have an adverse effect on endothelial function in overweight or obese diabetics because of the selective insulin resistance, potentially resulting in endothelial dysfunction." (PMID 34439553, 2021). "Interestingly, high-fat diet-induced insulin resistance abolished the effects of insulin on striatal dopamine release and reuptake, which could be restored with an insulin receptor sensitizing agent." (PMID 34331964, 2021). "During late pregnancy, insulin lessens its ability to suppress whole-body lipolysis; thus, in the postprandial period, greater increases in fatty acids and greater hepatic glucose production are observed, and this effect is more pronounced in women with insulin resistance/GDM." (PMID 33870263, 2021). "In conclusion, we have shown that GPR21 negatively affects insulin sensitivity in hepatocytes, suggesting that its inhibition might represent a novel and promising pharmacological strategy to counteract the development of insulin resistance." (PMID 34639123, 2021). "In support of this hypothesis, studies that have stratified participants by either insulin resistance or fasting insulin have showed that diet intervention outcomes differ according to phenotype, and that those with insulin resistance responded better to low-carbohydrate diets." (PMID 33572489, 2021).
Insulin resistance (continued). "Interestingly, insulin resistance induced by the deletion of one allele of the IR in osteoblasts decreased insulin sensitivity of the muscle and the WAT, highlighting the complex crosstalk that exists between insulin-sensitive tissues." (PMID 33435513, 2021). "Finally, the proposed CANi proved to be highly sensible and accurate for detecting salivary insulin with the sensitivity of 10 fg/ml and a linear range from 10 fg/ml to 1 ng/ml, which will be beneficial for early diagnosis and prevention of insulin resistance–related diseases." (PMID 34858958, 2021). "In addition, the BCAAs supplement may directly promote insulin resistance and the onset of T2D in both animals and humans, possibly via the disruption of insulin signaling." (PMID 34445047, 2021). "Moreover, TRE could be shown to significantly lower fasting insulin levels, as well as insulin resistance and increase insulin sensitivity." (PMID 34456861, 2021). "Therefore, we can speculate that IRB might decrease the insulin secretion pathway through improvement of insulin resistance to decrease LPN synthesis and secretion." (PMID 33570444, 2021). "Moreover, an animal study determined that intraperitoneal administration of adropin significantly reduces triglycerides, LDL and total cholesterol while also decreasing blood glucose, insulin levels, and homeostastic model assessment for insulin resistance (HOMA-IR) in rats with hyperlipidemia." (PMID 33920330, 2021). "Similarly, brain insulin resistance may be defined as the failure of brain cells to respond to insulin." (PMID 34576151, 2021). "Furthermore, oestrogen receptors (ERα and ERβ) are involved in insulin secretion and glucose uptake, which may be responsible for gender differences in insulin resistance." (PMID 34830194, 2021). "How insulin resistance develops at a cellular level can be explained by the fundamental relationship between the number of insulin receptors on the hormone’s target cells such as adipocytes, and the concentration of insulin needed to produce a biological response." (PMID 34836068, 2021). "First, intranasal insulin has been developed with the objective to efficiently deliver insulin directly into the brain without changing peripheral levels that could cause insulin resistance." (PMID 35087428, 2021). "Obesity is a recognised risk factor for insulin resistance but not all insulin-resistant individuals are overweight or obese; indeed, the existence of metabolically healthy obese and metabolically unhealthy normal weight individuals has been described in previous studies." (PMID 34110438, 2021). "The hypoglycemic effect of SGLT2i without increasing insulin secretion may result in body weight loss, which improves inflammatory state and insulin resistance, and induces an amelioration of oxidative stress, glucose and lipid metabolism, and BP." (PMID 33922546, 2021). "Furthermore, identifying how insulin modulates metabolic processes in the brain and individual cell types and how these are affected by insulin resistance may yield novel targets for therapeutic intervention." (PMID 33845179, 2021). "Thus, in liver cells from obese and high fat diet-fed mice, a decrease in LETM1 expression was associated with a reciprocal increase in CTMP expression and a decrease in Akt activity, suppression of insulin signaling and cellular glucose uptake, and development of insulin resistance." (PMID 33815143, 2021). "However, reduced insulin clearance may exacerbate insulin resistance via hyperinsulinemia-mediated desensitization." (PMID 34206745, 2021). "Moreover, obesity may mediate cancer progression through insulin resistance via the insulin/insulin-like growth factor axis, oxidative stress, chronic systemic inflammation, and dysregulated adipokines secretion." (PMID 34684639, 2021).
Insulin resistance (continued). "In fact, the borderline-significant trend towards an increase in fasting insulin and the up-regulation of inflammatory gene sets in adipose tissue after 4 week herbal supplementation may even point to a deteriorating effect on insulin resistance, glucose handling, HOMA-IR and adipose tissue health." (PMID 33477443, 2021). "Wu found that BSJPHX principle could significantly improve the clinical symptoms of TCM in patients with T2DOP, effectively reduce blood glucose and glycosylated hemoglobin, fasting insulin level and insulin resistance index, and improve BMD and serum IGF-1, IRS-1, IRS-2 levels." (PMID 33761702, 2021). "Furthermore, in obese humans, the circulating level of the EVs enriched with perilipin A was positively correlated with plasma insulin level and homeostatic model assessment of insulin resistance (HOMA-IR), supporting potential use of perilipin A-positive EVs as the biomarker of insulin resistance." (PMID 33717092, 2021). "The bioactive substances in tea, such as catechin, tea theaflavins, and caffeine, may play a role in enhancing insulin activity, ameliorating insulin resistance, activating the insulin-signaling pathway, protecting islet B cells, scavenging free radicals, and decreasing inflammation." (PMID 33709113, 2021). "Moreover, 2-hydroxybutyric acid, a marker of insulin resistance, was elevated after treatment with glimepiride but decreased on liraglutide treatment, possibly suggesting increased insulin resistance in the glimepiride group, and/or improved insulin sensitivity in the liraglutide group." (PMID 34920733, 2021). "We postulate that augmented hepatic IDE activity in response to glucose and insulin could serve as a mechanism that preserves hepatocytes from being exposed to high levels of portal insulin, resulting in the downregulation of the insulin receptor and appearance of insulin resistance." (PMID 34572095, 2021). "Interestingly, a mild level of impaired glucose metabolism is a feature of several genetic and pharmacological murine models that target the insulin signaling pathway to extend lifespan, and mild insulin resistance with proposed to be a protective mechanism during aging." (PMID 33503847, 2021). "In addition, it is difficult to understand how insulin resistance in subjects with normal glucose tolerance could be responsible for increased insulin secretion when blood glucose concentrations are still within the normal range." (PMID 34360563, 2021). "Additionally, chronic administration of the NOD2 ligand MDP either prior to the development of disease (preventatively) or after development of insulin resistance (therapeutically) resulted in improved insulin sensitivity and glucose tolerance in HFD fed wildtype mice." (PMID 33503814, 2021). "However, some of the milder forms (mainly type A insulin resistance) may have close to normal glucose tolerance in spite of congenital markedly elevated plasma insulin concentrations." (PMID 33555509, 2021). "In light of prior results, our study suggests that betaine, or other factors in its food sources of shellfish, wheat germ and bran, and spinach, could have protective effects for insulin resistance and insulin sensitivity, highlighting the need for further investigation." (PMID 34448864, 2021). "Moreover, calcium may up-regulate the insulin signaling pathway, thus reducing insulin resistance in obesity." (PMID 34064348, 2021). "Thus, it further results in hyper-secretion of insulin and leading to insulin resistance over time." (PMID 34667235, 2021). "Our data showed a positive association of HMGCR with insulin signaling pathway, particularly, PI3K signaling, and negative association with NF-κB signaling, which suggests that reduced activity of HMGCR could contribute to insulin resistance." (PMID 34564389, 2021).